MYCN (MYCN proto-oncogene, bHLH transcription factor)
Diseases named in the same sentence as MYCN in open-access papers (continued):
Sharing a sentence is not in itself a finding about the gene and the disease.
neuroblastoma (continued). "This positive autoregulatory loop may function in primary human neuroblastomas to enhance metastasis as well as drug resistance through stabilization of MYCN and even β-catenin, which are mediated by inhibition of GSK3β." (PMID 24391509, 2014). "Consistent with this, our results indicate that NCYM expression is associated with poor outcomes in human neuroblastoma regardless of genomic status of the MYCN/NCYM locus." (PMID 24391509, 2014). "Furthermore, the survival of MYCN transgenic mice bearing neuroblastoma was improved by treatment with NVP-BEZ235, a dual PI3K/mTOR inhibitor shown to destabilize MYCN via GSK3β activation." (PMID 24391509, 2014). "Taken together these data provide compelling evidence that JQ1 down regulates c-MYC driven transcription in medulloblastoma cell lines; these data are consistent with activity observed in hematologic malignancies and analogous to that seen in MYCN driven neuroblastoma." (PMID 24796395, 2014). "Importantly, 10074-G5 and 10058-F4 were the most efficient in inducing neuronal differentiation and lipid accumulation in MYCN-amplified neuroblastoma cells." (PMID 24859015, 2014). "Even if the mechanism through which MYCN mediates tumorigenesis remains largely unknown, experimentally induced downregulation of MYCN in neuroblastoma cells leads to growth arrest and cell death in vitro and decreased incidence and tumor mass in vivo." (PMID 24334727, 2014). "One of the mechanisms by which MYC and MYCN are destabilized in S(+)-ibuprofen-treated neuroblastoma cells may be due to the augmented activation of calpains in response to UPR." (PMID 24173829, 2014). "Furthermore, NCYM co-immunoprecipitated with GSK3β and substrates of GSK3β such as MYCN and β-catenin were stabilized in the neuroblastoma tissues induced in MYCN/NCYM transgenic mice." (PMID 24391509, 2014). "Similarly, MYCN-amplified neuroblastoma cells are addicted to high levels of MYCN in tissue culture." (PMID 24759734, 2014). "Interestingly, suppression of CDK2 activity is required for reduced proliferation and survival of the primary neural crest derived tumour and its inhibition was demonstrated to be synthetic lethal in MYCN overexpressing neuroblastoma." (PMID 25594028, 2014). "Because NCYM binds directly to MYCN both in vitro and in neuroblastoma cells, this may affect the recruitment of the regulators of MYCN stability." (PMID 24391509, 2014). "Since patients with MYCN-amplified neuroblastoma have a poor prognosis, targeting MYCN using small molecule inhibitors could represent a promising therapeutic approach." (PMID 24859015, 2014). "Furthermore, our study showed that NCYM knockdown significantly induces apoptosis in MYCN-amplified neuroblastoma cells, whereas the effects were marginal in MYCN-single neuroblastoma cells." (PMID 24391509, 2014). "Interestingly a recent report also demonstrates that JQ1 alters MYCN driven transcription in neuroblastoma suggesting the potential for targeting of multiple MYC family members with JQ1." (PMID 24796395, 2014). "MYCN and MYC play a crucial role in determining the malignancy of unfavorable neuroblastomas, whereas high-level expression of the favorable neuroblastoma genes is associated with a good disease outcome and confers growth suppression of neuroblastoma cells." (PMID 24173829, 2014). "Besides the more frequently found “classical,” i.e., homogeneous, MYCN amplification, neuroblastomas can also show intratumoral heterogeneity for the MYCN status, clearly detectable by the use of FISH techniques, which allow the identification of single cells." (PMID 25161957, 2014). "Indeed, miR-380-5p is highly expressed in neuroblastomas with neuroblastoma-derived v-myc myelocytomatosis viral-related oncogene (MYCN) amplification, and the high expression level correlates with poor diagnosis." (PMID 25302307, 2014).
neuroblastoma (continued). "The aim of this study was to examine and compare the ultrastructural features of high-risk MYCN amplified neuroblastomas, with lower-risk non-MYCN amplified tumours." (PMID 24679140, 2014). "MYCN amplification is a major negative prognostic factor in neuroblastoma indicating high-risk disease." (PMID 25268132, 2014). "The MYCN status is used in all current neuroblastoma clinical trials." (PMID 25161957, 2014). "We performed also multivariate Cox proportional hazard analysis and investigated the effect of CASP8 SNP D302H on the survival of neuroblastoma patients taking into account the different clinical covariates (stage of the disease, MYCN status, and the age at diagnosis)." (PMID 25502557, 2014). "Additionally, inhibition of this pathway at the level of GLI1 is more potent than SMO blockade in reducing the cellular proliferation of non-MYCN amplified neuroblastoma cell lines." (PMID 25134527, 2014). "MYCN is overexpressed, frequently as a consequence of genomic amplification, in a large number of childhood malignancies, such as neuroblastoma, rhabdomyosarcoma and medulloblastoma, and enhanced MYCN expression correlates with increased growth potential and dismal prognosis." (PMID 24334727, 2014). "This suggests that GLI1 inhibition of HH signaling is an effective way to target high-risk neuroblastoma without MYCN amplification and should be considered as an option for neuroblastoma treatment." (PMID 25134527, 2014). "NCYM is a cis-antisense gene of MYCN and is co-amplified with MYCN in human neuroblastoma cells." (PMID 24391509, 2014). "Indeed, we have recently found that the tumor suppressor protein Runx3 directly binds to MYCN in neuroblastoma cells and promotes degradation of MYCN in the ubiquitin–proteasome system dependent manner." (PMID 24391509, 2014). "We show that in ALK-mutated, MYCN-amplified neuroblastoma cells, crizotinib alone does not affect mTORC1 activity as indicated by persistent RPS6 phosphorylation." (PMID 25228590, 2014). "While neuroblastoma is one of the most common childhood malignancies, in adults it is extremely rare and its treatment is based on pediatric protocols that take into consideration stage and genotypic features, such as MYCN amplification." (PMID 24396620, 2013). "Amplification or over-expression of MYCN or MYCL1 is frequently observed in lung cancer (MYCN, MYCL1), ovarian cancer (MYCL1), breast cancer (MYCN), and cancers of neural origin including glioblastoma (MYCL1, MYCN), medulloblastoma (MYCN), and neuroblastoma (MYCN)." (PMID 24009722, 2013). "It is important to note that sensitivities to panobinostat for these high-risk neuroblastoma cell lines are independent of the status of MYCN amplification." (PMID 24098799, 2013). "Overexpression of MYCN in neuroblastoma has been correlated with treatment failure; the inhibition of MYCN expression may prove to be a useful target for treatment of neuroblastoma." (PMID 24459422, 2013). "It should also be noted that MYCN expression is down regulated in neuroblastoma cells after treatment with RA, so if PPARδ1 expression is repressed directly or indirectly by MYCN, its potential up-regulation in response to RA would act as a compensatory cell-survival and cell-growth mechanism." (PMID 23874790, 2013). "To determine the differences in phosphopeptide abundance in neuroblastoma cells compared with normal neural crest-derived cells, we isolated proteins from the NB10 cell line, representing a high-risk MYCN amplified cell line, and from an NPC line, representing a control human neural crest cell line." (PMID 24349301, 2013). "Moreover, a role for GRP/GRP-R/AKT axis in the regulation of the MYCN oncogene in neuroblastoma is yet to be studied." (PMID 23468863, 2013).
neuroblastoma (continued). "Therefore, a picture is emerging of a darwinistic genetic wiring in neuroblastoma cells in which multiple events strive to increase MYCN downstream activity." (PMID 23308108, 2013). "We recently identified the miR-17∼92 cluster as an important mediator of MYCN signaling in neuroblastoma with several components of this cluster down regulating expression of target genes such as DKK3 and members of the TGFβ pathway that contribute to the MYCN driven tumor phenotype." (PMID 23308108, 2013). "A member of Dickkopf (DKK) family, DKK1, is down-regulated by MYCN in neuroblastoma and this might contribute to the well-documented stimulation of cell proliferation by MYCN." (PMID 23482921, 2013). "More specifically, we show here that a significant proportion of such focal copy number changes target genes implicated in MYCN signaling and may therefore reinforce the oncogenic effect of MYCN (or MYC) on neuroblastoma cells." (PMID 23308108, 2013). "This indicates that folate-nanoliposome entrapped MYCN siRNA could be used in future gene therapy of neuroblastoma." (PMID 23806172, 2013). "TrkB is expressed in many MYCN-amplified neuroblastoma tumors." (PMID 24349301, 2013). "Overexpression of MYCN caused by the disruption of the protein degradation but not by the amplification indicated poor outcome in patients with neuroblastoma." (PMID 23679233, 2013). "However, recent several lines of evidence have revealed that MYCN can repress at least as many genes as it activates, thus proposing a novel function of this protein in neuroblastoma biology." (PMID 23482921, 2013). "It would seem that MNA tumors are more proliferative, which calls for a dose-intensive treatment, and the relatively “clean” genetics of MNA neuroblastomas would appear to make them suitable for tailored treatments that target the functions of MYCN, e.g. apoptosis." (PMID 23656755, 2013). "Nowadays it is well established that MYCN plays a pivotal role in neuroblastoma tumorigenesis." (PMID 23482921, 2013). "In this study, we want to further investigate whether folate receptor-targeted liposome can act as a good delivery tool of MYCN siRNA and exert a satisfying therapeutic effect on neuroblastoma." (PMID 23806172, 2013). "Besides miR-591, a short tumor suppressor RNA, is down-regulated in neuroblastomas with MYCN amplification." (PMID 23482921, 2013). "Furthermore, inhibition of PI3K destabilized MYCN and prevented tumor progression in a murine model of neuroblastoma." (PMID 23597230, 2013). "Also, it has been shown that the ODC inhibitor DFMO increased tumor-free survival in TH-MYCN mice, which over express MYCN in neural lineages and develop neuroblastomas." (PMID 23840755, 2013). "Moreover, Gli1 overexpression has been shown to decrease the mitotic index of MYCN-amplified neuroblastoma cells." (PMID 23900341, 2013). "Our analysis, although limited in scope to a single MYCN-amplified cell line, identified many elevated phosphopeptides from proteins within the neuroblastoma phosphoproteome that could be targeted therapeutically to inhibit tumor growth." (PMID 24349301, 2013). "Then we examined whether folate-nanoliposomes entrapped MYCN siRNA can specifically distribute to tumor tissues and suppress MYCN gene expression as well as induce apoptosis in neuroblastoma cells." (PMID 23806172, 2013). "MYCN oncogene amplification is the most important prognostic factor in neuroblastoma." (PMID 24131700, 2013).
neuroblastoma (continued). "Furthermore, consistent with the observation that AURKA is required for growth of MYCN amplified neuroblastoma, cells expressing high levels of MYCN were more sensitive to CCT137690 in comparison to cells expressing low or no MYCN." (PMID 23226679, 2012). "Somehow paradoxically, MYCN also sensitizes neuroblastoma cells to apoptosis, understanding the molecular mechanisms of which might be relevant for the therapy of MYCN amplified neuroblastoma." (PMID 23152863, 2012). "Given their reliance on B-MYB, neuroblastoma tumours with amplification of MYCN should be exquisitely sensitive to its pharmacological targeting, suggesting that small molecule inhibitors of B-Myb could have important clinical applications." (PMID 22619121, 2012). "Consequently, the MYCN oncogene has been characterized extensively and in mice, its targeted expression toward neuroectodermal cells drives the development of neuroblastoma." (PMID 23267433, 2012). "Interestingly the ampGR within the iAMP21-amplicon were found exclusively arranged head-to-head and tail-to-tail, in contrast to the investigated MYCN-amplicons in primary neuroblastomas, in which all ampGR had been found in head-to-tail orientation." (PMID 23210797, 2012). "A MYCN transgenic mouse model (TH-MYCN mice), which faithfully recapitulates the features of human neuroblastoma with similar biochemical features and syntenic chromosomal rearrangements to human neuroblastoma, was used." (PMID 23181218, 2012). "Meanwhile, there are several genes which mediate the miR-34a induced tumor growth inhibition, such as BCL2, E2F3 and MYCN in neuroblastoma, mitogen-activated protein kinase kinase 1 (MEK1) in human chronic myelocytic leukemia cell line K562 and SIRT1 in prostate cancer PC3 cells." (PMID 22457788, 2012). "Since MYCN is upstream of the polyamine biosynthesis pathway, this suggests a major role for MYCN in regulating polyamine biosynthesis, and a mechanism by which MYCN contributes to neuroblastoma development." (PMID 23181218, 2012). "The polyamine pathway is frequently deregulated in neuroblastoma, and a number of genes involved in polyamine homeostasis are known to be MYCN or c-MYC targets, while the expression of others is linked to MYCN status." (PMID 23181218, 2012). "Thus, MYCN sensitizes neuroblastoma cells to apoptosis by upregulation of the HIPK2/p53Ser46 pathway via ATM-dependent DNA damage response (DDR) that activates HIPK2." (PMID 22889244, 2012). "Furthermore, the ability to examine pharmacological inhibition of MRP4 using in vitro and in vivo models will offer a tool with which to gain greater insight into its role in the transcriptional program of MYCN in neuroblastoma." (PMID 23267433, 2012).
neuroblastoma (continued). "It has been suggested that deregulated MYCN expression in MYCN amplified neuroblastoma indirectly upregulates SKP2 via the induction of CDK4, thereby reducing the abundance of repressive pRB-E2F1 complexes bound to the SKP2 promoter and providing an entry point into the SKP2 autoinduction loop." (PMID 23226679, 2012). "Also, the region was reported to be methylated almost exclusively in neuroblastomas with MYCN amplification." (PMID 22984959, 2012). "This approach has recently been developed and described for MYCN amplified neuroblastomas." (PMID 23210797, 2012). "Comparable to amplification of MYCN in childhood neuroblastomas, iAMP21 including AML1/RUNX1 is discussed to be an initial event in the development of leukemic blasts comprising this genomic lesion, and no information exists that AFS change over time within these cells." (PMID 23210797, 2012). "In this previous work, a genome-wide search for MYCN targets was performed to identify clusters of genes that were directly regulated by MYC/MYCN or indirectly involved in MYCN-induced regulation, using a neuroblastoma cell line that allows conditional expression of MYCN." (PMID 23251412, 2012). "Polyamine sufficiency may be required for MYCN oncogenicity in MYCN amplified neuroblastoma, and targeting polyamine homeostasis may therefore provide an attractive therapeutic approach." (PMID 23181218, 2012). "MYCN serves as a prognostic marker for neuroblastoma and is a central regulator of the cell cycle." (PMID 23251412, 2012). "We concluded this method is suitable for MRD quantification of MYCN amplified neuroblastoma." (PMID 23210797, 2012). "However, the genes necessary or sufficient to initiate neuroblastoma tumorigenesis downstream of MYCN remain to be established." (PMID 23181218, 2012). "Neuroblastoma is a common childhood solid tumour in which MYCN is amplified in ∼15% of cases." (PMID 21654684, 2011). "Despite its clinical significance, it is still largely unknown how MYCN expression is regulated in neuroblastoma." (PMID 21654684, 2011). "The goal was to identify stage- and MYCN amplification-specific splicing patterns in comparison to whole gene expression changes for the understanding of cancer biology and discovery of biomarkers or therapeutic targets in neuroblastoma." (PMID 21501490, 2011). "The focus was high-risk neuroblastoma, with a small number of clinical stage 4 samples with MYCN amplified and stage 1's with MYCN not amplified." (PMID 21619611, 2011). "It is still important to emphasize that the majority of metastatic tumours do not show amplification of the MYCN oncogene, and other chromosomal aberrations are being evaluated for the International Neuroblastoma Risk Group (INRG) classification system." (PMID 21492432, 2011). "MYCN is the most important biologic marker for neuroblastoma." (PMID 21501490, 2011).